TPI1 (triosephosphate isomerase 1)
Diseases named in the same sentence as TPI1 in open-access papers (continued):
Sharing a sentence is not in itself a finding about the gene and the disease.
dental fluorosis (1 paper, 2022). A condition that results from excessive fluoride ingestion during tooth development, resulting in tooth discoloration ranging from white streaks to brown stains and cracks or pits in the tooth enamel. "The KGML network diagram showed that the proteins (LDHA, ENO3, GPI, and TPI1) enriched in the HIF-1 and glycolysis/gluconeogenesis pathways have a direct correlation with the formation of dental fluorosis." (PMID 35897842, 2022). "The up-regulation of ENO3, LDHA, TPI1, and GPI implies that the HIF-1 pathway and glycolysis/gluconeogenesis pathway are strengthened in ameloblasts, which affects the energy harvesting of ameloblasts and leads to the formation of dental fluorosis." (PMID 35897842, 2022).
emphysema (1 paper, 2019). "The expression of triosephosphate isomerase 1 (Tpi1) is low in smoking-induced emphysema lung models." (PMID 30770755, 2019).
epilepsy (1 paper, 2025). A brain disorder characterized by episodes of abnormally increased neuronal discharge resulting in transient episodes of sensory or motor neurological dysfunction, or psychic dysfunction. "In addition, the mTOR pathway genes RPS6, TPI1, ENO1, and PGK1 are enriched in PY2-like cortical neurons of brain samples from patients with epilepsy compared with people in a nonepilepsy control group." (PMID 40026248, 2025).
Hypertension (1 paper, 2017). The presence of chronic increased pressure in the systemic arterial system. "Moreover, the effect of Tianma on correcting the function and activity of Tpi1, Ppia, Ncam1, Uchl1, Septin-2 and Hsp90aa1 proteins, provided conclusive evidence for Tianma in the treatment of seizures, hypertension and headaches." (PMID 29262557, 2017).
lymph node metastasis (1 paper, 2025). "Additionally, TPI1 levels positively correlated with histologic grade, invasion depth, and lymph node metastasis, and higher TPI1 expression was associated with worse overall survival (OS) in the cohort." (PMID 40427052, 2025).
mastitis (1 paper, 2022). Inflammation of breast tissue during lactation or postpartum due to an obstructed duct or infection. "When mastitis developed (T1/C1), GPI, TPI1, GAPDH, PGK1, PGAM1, ENO1, and PKM in the glycolysis/gluconeogenesis pathway were upregulated, which promoted pyruvate synthesis with large amounts of ATP production." (PMID 36335251, 2022).
Moyamoya disease (1 paper, 2021). Moyamoya disease (MMD) is a rare intracranial arteriopathy involving progressive stenosis of the cerebral vasculature located at the base of the brain causing transient ischemic attacks or strokes. "Therefore, TPI1 may inhibit the size of tumors and induce Moyamoya disease." (PMID 33747055, 2021).
preeclampsia (1 paper, 2013). Preeclampsia is a hypertensive disorder of pregnancy that is characterized by new-onset hypertension with proteinuria presenting after 20 weeks of gestation, and depending on mild or severe forms may initially present with severe headache, visual disturbances, and hyperreflexia. "Other genes as SPAG4, HEXB, TPI1 and QSOX1 are basically unknown in preeclampsia (and even during normal pregnancy)." (PMID 24219996, 2013).
salivary gland tumors (1 paper, 2024). "Some of the identified peptides were derived from proteins previously suggested as potential biomarkers of salivary gland tumors (ANXA1, BPIFA2, FGB, GAPDH, HSPB1, IGHG1, VIM) or tumors of other tissues or organs (SERPINA1, APOA2, CSTB, GSTP1, S100A8, S100A9, TPI1)." (PMID 39201484, 2024).
testicular tumor (1 paper, 2025). "In addition to SPTBN4, 31 other molecules were analyzed, revealing potential testicular tumor markers such as TPI1, HMGN1, UGCG, NCL, SET, and EIF3K." (PMID 40321316, 2025).
cancer (66 papers, 2010 to 2026). A tumor composed of atypical neoplastic, often pleomorphic cells that invade other tissues. "In terms of its metabolic influence, TPI1 has been implicated in promoting oral cancer, liver cancer occurrence, and metastasis by modulating glycolytic levels within cancer cells." (PMID 38102653, 2023). "Studies have shown that TPI1 is associated with various cancers." (PMID 41429797, 2025). "Similarly, the glycolytic enzymes Pkm2, Tpi1, Pgam2, and Pfkl are known to be highly expressed in various cancers, and are associated with poor prognosis." (PMID 31336728, 2019). "Our findings showed that TPI1 expression was significantly higher in cancer tissues than in normal oral tissues." (PMID 40427052, 2025). "TPI1 is overexpressed in multiple cancers, such as intrahepatic cholangiocarcinoma, gastric, lung, and prostate cancers, and its elevated expression has been correlated with poor clinical outcomes." (PMID 40427052, 2025). "Triosephosphate isomerase 1 (TPI1), a key glycolytic enzyme, has been implicated in cancer progression, but its role in ferroptosis regulation, particularly in the context of chemoresistance, is largely unexplored." (PMID 40427052, 2025). "These divergent findings underscore the complexity of TPI1’s role in cancer biology and the necessity to investigate its function in specific tumor contexts." (PMID 40427052, 2025). "circ-231 promotes the unwinding of 5′ UTRs of TPI1 and PRDX6 mRNAs, which is associated with the migration and proliferation of cancer cells, suggesting that circ-231 plays a critical role in cancer cells." (PMID 38577609, 2024). "Quantities of studies demonstrate that glycolytic reprograming is essential for the progression of cancers, where triosephosphate isomerase 1 (TPI1) serves as a catalytic enzyme." (PMID 38102653, 2023). "The role of TPI1 in cancer is controversial due to its expression and functions in different cancer types." (PMID 34401050, 2021). "Despite the fact that TPI1 seems to have a contradictory function in cancer, its inhibitory role in HCC has been reported." (PMID 34401050, 2021). "Cellular metabolism and transportation related genes (ALDOA, SLC16A3, TPI1, LDHB, KCNQ5, and PGM1), which are implicated in human cancer, also remained upregulated even 2-month after radiation exposure." (PMID 23216862, 2012). "TPI1 is a glycolytic enzyme that is thought to have some relevant roles in cancer." (PMID 39997396, 2025). "However, the knowledge of TPI1 in cancer is limited and is thought to be related to gene sharing and moonlighting functions." (PMID 39997396, 2025). "Therefore, we conclude that circ-231 is involved in migration and proliferation of cancer cells through mediating the synthesis of TPI1 and PRDX6 proteins." (PMID 38577609, 2024). "The biological processes related to cancer development, signaling, and response comprised 12 distinct hallmark pathways enriched with genes related to hypoxia, including Enolase 1 (ENO1), Triosephosphate isomerase (TPI-1), Decorin (DEC) Fos- proto-oncogene gene (FOS), and Aldolase-(ALDO)." (PMID 39063015, 2024). "TPI1 is overexpressed in multiple cancers, such as BC tissues and cell lines or LUAD." (PMID 37834160, 2023). "It is of interest to explore whether similar mechanism is also applicable for TPI1 in the regulation of other types of cancers." (PMID 35246510, 2022). "Despite these reports, the knowledge or TPI1 in cancer is limited." (PMID 35246510, 2022). "Moreover, nuclear translocation of TPI1 is induced by extracellular stress (such as chemotherapy agents and peroxide), which facilitates the chemoresistance of cancer cells." (PMID 35246510, 2022). "TPI1 (triosephosphate isomerase 1) was overexpressed in various types of cancers and might be induced by hypoxia in pan-cancer." (PMID 35757722, 2022). "Consistently, the mRNA and protein expressions of OTUB2, EIF4A3, and TPI1 were increased in TNBC tissues and cell lines, as compared to para-carcinoma tissues and MCF10A cells." (PMID 41857621, 2026).
cancer (continued). "Human triosephosphate isomerase (TPI1) is a key glycolytic enzyme, and glycolysis is accelerated in cancer cells." (PMID 38249992, 2024). "In particular, c-MYC and HIF-1α promote the expression of glycolytic enzymes hexokinase 2 (HK2), phosphofructokinase 1 (PFK1), triosephosphate isomerase 1 (TPI1), lactate dehydrogenase A (LDHA) in cancer." (PMID 36313705, 2022). "Relative PAM, STC1, and HDAC4 expression were down-regulated, whereas CASP6, CHST6, SLC16A3, TPI1, KDELR3, VCAN, and CLDN9 were highly expressed in carcinoma tissues compared to the para-carcinoma tissues." (PMID 33424916, 2020). "In our study, we propose that the chr12p13 gain leads to the over-expression of genes annotated in this genomic region (i.e., GAPDH, TPI1, FOXM1) creating cancer-specific metabolic addiction." (PMID 30873387, 2019). "Four enzymes (TPI1, AKR1B10, ALDOA, and AKR1B1) out of 34 enzymes in this pathway are overexpressed in cancer." (PMID 25243088, 2014). "Expression of genes within the glycolytic pathway (GAPDH, TPI1 and GPI) remained highly correlated in both in NSCLCs and non-cancer control tissue samples." (PMID 23620736, 2013). "Since TPI1 regulates the interconversion between DHAP and G3P, its dysregulation may disturb glucose metabolism and thereby facilitate cancer progression." (PMID 41206438, 2025). "Additionally, the TISCH2 indicated that all the hub-genes of cancer cells were upregulated in malignant cells, especially GAPDH, RHOA, TPI1, H4C6, DDX21, and APEX1, which showed considerably high expression levels in malignant cells." (PMID 40906153, 2025). "Moreover, TPI1 silencing disrupted the epithelial–mesenchymal transition (EMT), a key driver of cancer metastasis and drug resistance." (PMID 40427052, 2025). "We observed that TPI1 or PRDX6 knockdown resulted in the inhibition of the migration and proliferation of cancer cells and the knockdown inhibited the migration of cancer cells, although, in KYSE150, the proliferation of cancer cells was not altered after PRDX6 knockdown." (PMID 38577609, 2024). "Previous studies showed that TPI1 and PRDX6 protein played a critical role in cancer cells." (PMID 38577609, 2024). "On the non-metabolic front, TPI1 has been found to enhance overall histone acetylation during the cell cycle, a critical factor in cancer-related cellular processes." (PMID 38102653, 2023). "The authors found that in endometrial and EOC BMs, the expression of alpha-enolase (ENO1) and triosephosphate isomerase (TPI-1) was higher and the expression of Transgelin-2 (TAGLN2) was lower compared to primary cancers, suggesting a role in development and progression of BMs." (PMID 34943916, 2021). "However, significant enhancement of ALDOA, TPI1, and DNAJB1 in MD/PD/WD metastatic OSCC compared to WD OSCC suggests enhanced cancer cell proliferation, metabolic reprogramming and oncogenic stress in the former." (PMID 32922662, 2020). "Notably, TPI1 in primary BRCA was significantly higher than that in normal breast tissue, as well as in 112 pairs of cancer and noncancerous adjacent tissues." (PMID 35509067, 2022).
tumor (62 papers, 2008 to 2026). "We assessed the potential associations of the TPI1 expression with patients' clinicopathological factors, such as age, gender, tumor stage, and smoking history." (PMID 35126788, 2022). "Elevated TPI1 expression is associated with high levels of metabolism required for rapid tumor growth." (PMID 35610567, 2022). "We also explored the associations of TPI1 with tumor microenvironment and its expression levels in various immune cells." (PMID 35126788, 2022). "It was revealed that TPI1 expression was positively correlated with overall survival and negatively associated with tumor size and histological differentiation." (PMID 35126788, 2022). "TPI1 is a crucial enzyme in carbohydrate metabolism, negatively associated with tumor size." (PMID 33747055, 2021). "We speculated that the uptake of EVs with reduced TPI1 might cause glycolytic reprogramming in the recipient cells, which in turn favours tumour progression." (PMID 34401050, 2021). "CONCLUSIONS: We conclude that OTUB2 deubiquitinates and stabilizes EIF4A3 to promote TNBC progression via TPI1-mediated glycolysis of tumor cells." (PMID 41857621, 2026). "In vivo, TPI1 depletion resulted in marked tumor growth inhibition and synergized with cisplatin to further suppress tumor burden in xenograft models." (PMID 40427052, 2025). "Our findings expand on these observations by illustrating that TPI1 also plays a suppressive role in ferroptosis, a death pathway gaining increasing attention for its potential to eliminate therapy-resistant tumor cells." (PMID 40427052, 2025). "While it can act as a suppressor under specific experimental conditions, deregulated TPI1—particularly in extracellular vehicles (EVs)—has been shown to promote aerobic glycolysis and enhance tumor aggressiveness." (PMID 41206438, 2025). "The results showed that, compared to the control group, tumor volumes were significantly reduced in both the TPI1-knockdown group and the gemcitabine-treated group." (PMID 41429797, 2025). "More importantly, the combination of TPI1 knockdown and gemcitabine treatment led to a further reduction in tumor volume compared to gemcitabine treatment alone." (PMID 41429797, 2025). "In an in vivo tumor model, the cisplatin injection demonstrated that TPI1 inhibition improved treatment outcomes, reducing tumor weight and volume." (PMID 40427052, 2025). "Ki67 IHC staining revealed that TPI1 knockdown combined with cisplatin most effectively inhibited tumor growth." (PMID 40427052, 2025). "To gain more insight into the role of TPI1 translocation in tumor chemoresistance, we performed xenograft tumor growth assay by injecting nude mice subcutaneously with TPI1-NLS and TPI1-NES cells." (PMID 35246510, 2022). "In this article, we systematically screened metabolic enzymes in glycolysis and gluconeogenesis pathway which are essential for tumor development and found that TPI1 is upregulated in a variety of tumors and closely related to patients’ prognosis." (PMID 35246510, 2022). "For example, EDK89777.1 has homology with human triosephosphate isomerase (TPI) 1 which is one of the most important hallmarks for fast-growing tumor cells." (PMID 35574378, 2022). "In vitro and in vivo experiments demonstrated that nuclear-localized TPI1 significantly improved tumor cell resistance to chemotherapy." (PMID 35246510, 2022). "TPI1 exhibited significantly higher expression in tumor tissues than in adjacent normal tissues, which is consistent with the western blot result of LUAD tissues." (PMID 35246510, 2022). "To confirm the result, we examined TPI1 expression in 12 pairs of clinical LUAD tumor and adjacent normal tissue samples, and found a significant increase of TPI1 protein level in LUAD tumors." (PMID 35246510, 2022). "Significant accumulation of TPI1 in cell nucleus was observed in LUAD tumor tissues compared with the cytoplasm localization in adjacent normal tissues." (PMID 35246510, 2022).
tumor (continued). "Our study provides insights in understanding the potential roles of TPI1 in tumor progression and immune microenvironment." (PMID 35126788, 2022). "We further demonstrated that TPI1 is important for cell migration, colony formation and xenograft tumor growth of LUAD cells." (PMID 35246510, 2022). "The results strongly support that nuclear-localization of TPI1 induced by stress conditions promotes tumor cell survival and increases cell resistance to chemotherapy." (PMID 35246510, 2022). "Strikingly, we also observed predominant nuclear staining of TPI1 in tumor tissues, compared to the predominant cytoplasmic staining in normal tissues." (PMID 35246510, 2022). "Our study provides insights in understanding the potential roles of TPI1 in tumor progression and immune microenvironment, which lay the foundation for future clinical research." (PMID 35126788, 2022). "Additionally, we observed that TPI1 expression was significantly upregulated in tumor tissues from Gem-resistant BCa patients compared to those from Gem-sensitive patients, suggesting a potential link between TPI1 and chemotherapy resistance in BCa." (PMID 41429797, 2025). "Multivariate analysis identified TPI1 as an independent prognostic factor for tumor progression." (PMID 40427052, 2025). "H&E staining and IHC results showed that TPI1 was upregulated in tumor tissues." (PMID 38921479, 2024). "In the present study, both circ-231 and eIF4A3 were overexpressed in ESCC and participated in TPI1 and PRDX6 mRNA initial translation, suggesting that both circ-231 and eIF4A3 were involved in tumor progression via post-transcriptionally regulating the expression of TPI1 and PRDX6." (PMID 38577609, 2024). "The catalytic inhibitor of SHP-1, TPI-1, has been explored as a potential anti-tumor immunotherapy." (PMID 38022587, 2023). "The tumors growth curve and tumor weight were higher for TPI1 group than vector control." (PMID 35509067, 2022). "Moreover, we analyzed the potential relations of TPI1 with immune cell infiltrations in the tumor microenvironment based on previous literatures and bioinformatic tools." (PMID 35126788, 2022). "In contrast, TPI1 inhibits liver tumor growth, differently functioning in tumor types." (PMID 36077431, 2022). "Furthermore, we explored the potential distribution and changes of TPI1 expression in tumor microenvironment." (PMID 35126788, 2022). "The role of TPI1 in tumor development is complicated and largely unclear so far." (PMID 35246510, 2022). "In addition, based on IHC, expression levels of CDCA5, Ki67, p-mTOR, and LDHA were higher in tumor tissue generated by TPI1 overexpression cells than vector control; E-cadherin was lower in these tumors." (PMID 35509067, 2022). "Importantly, univariate and multivariate analyses indicated that TPI1 expression level, tumor size and lymph node status were independent indicators for BRCA prognoses." (PMID 35509067, 2022). "Collectively, TPI1 promotes tumor development and progression, which may serve as a therapeutic target for BRCA." (PMID 35509067, 2022). "When TPI1 was knocked down, tumor size was reduced in shTPI1 group than NC group." (PMID 35509067, 2022). "In GSE127465 cohort, TPI1 was mainly expressed in dendritic cell, macrophage, and tumor cell." (PMID 35126788, 2022). "Notably, our data showed a significant elevation of TPI1 in ESCC patients with its level being positively correlated with tumor TNM stage (R2 = 0.33, P = 9.1e−4)." (PMID 35610567, 2022). "Moreover, we analyzed the potential relations of TPI1 with immunomodulators and immune cell infiltrations in the tumor microenvironment based on previous literatures and bioinformatic tools." (PMID 35126788, 2022). "Histologic analyses of primary tumor tissues consistently showed that TPI-1 treatment alone increased CD8 infiltration, which was further increased when anti-PD-1 was combined with SHP-1 inhibition with no observed effect on collagen deposition in either treatment group." (PMID 32908154, 2020).